ARHGAP21 (Rho GTPase activating protein 21)
Description:
Functions as a GTPase-activating protein (GAP) for RHOA and CDC42. Downstream partner of ARF1 which may control Golgi apparatus structure and function. Also required for CTNNA1 recruitment to adherens junctions.
Synonyms: ARHGAP10; KIAA1424
Tractability: Small molecule: a structure with a bound ligand is known. Antibody: its Gene Ontology location is reachable by antibodies, with high confidence; UniProt places it where antibodies can reach, with medium confidence. PROTAC: UniProt records ubiquitination sites on it; ubiquitination databases record sites on it; its protein half-life has been measured.
Gene: Protein-coding gene on chromosome 10 (24,583,609 to 24,723,887, reverse strand). Ensembl gene ENSG00000107863.
Subcellular location: Golgi apparatus membrane; Cell junction; Cytoplasmic vesicle membrane; Cytoplasm, cytoskeleton
Subcellular location (Human Protein Atlas): Cell Junctions; Plasma membrane; Actin filaments
Pathways (Reactome):
Signal Transduction: CDC42 GTPase cycle; RAC1 GTPase cycle; RAC2 GTPase cycle; RAC3 GTPase cycle; RHOA GTPase cycle; RHOB GTPase cycle; RHOC GTPase cycle; RHOD GTPase cycle; RHOF GTPase cycle; RHOG GTPase cycle; RHOJ GTPase cycle; RHOQ GTPase cycle; RND3 GTPase cycle
Gene Ontology:
Molecular function: protein binding; GTPase activator activity
Biological process: establishment of Golgi localization; Golgi organization; maintenance of Golgi location; organelle transport along microtubule; Golgi localization; regulation of small GTPase mediated signal transduction; signal transduction
Cellular component: actin cytoskeleton; cell junction; Golgi apparatus; cytosol; anchoring junction; cytoplasmic vesicle membrane; cytoskeleton; Golgi membrane
Genetic constraint (gnomAD): Loss-of-function variants: 26 observed, 138.1 expected, observed/expected ratio (o/e) 0.19, 90% interval 0.14 to 0.26. The upper end of that interval is the gene's LOEUF score, 0.26, which puts it in group 1 of 6, group 1 being the genes least tolerant of losing a copy. Missense variants: 1,735 observed, 2,283.7 expected, observed/expected ratio (o/e) 0.76, 90% interval 0.73 to 0.79. Synonymous variants: 734 observed, 827.27 expected, observed/expected ratio (o/e) 0.89, 90% interval 0.83 to 0.94.
Homologues: Orthologues: chimpanzee ARHGAP21 (99% identical), macaque ARHGAP21 (98% identical), guinea pig ARHGAP21 (89% identical), pig ARHGAP21 (89% identical), mouse Arhgap21 (87% identical), rat Arhgap21 (86% identical), dog ARHGAP21 (83% identical), rabbit ARHGAP21 (66% identical), tropical clawed frog arhgap21 (63% identical), zebrafish arhgap21a (50% identical), zebrafish arhgap21b (48% identical). Paralogues in human: ARHGAP23 (31% identical).
Diseases named in the same sentence as ARHGAP21 in open-access papers:
ARHGAP21 is named in the same sentence as 22 diseases in open-access papers, as found by Europe PMC text mining. Sharing a sentence is not in itself a finding about the gene and the disease. The quoted sentences say what the papers report.
prostate carcinoma (3 papers, 2023 to 2025). A carcinoma that arises from epithelial cells of the prostate gland. "In prostate cancer, ARHGAP21 affects tumor progression by regulating the expression of the PCA3 gene, but its specific role in GC is still unclear." (PMID 40191191, 2025). "We showed that ARHGAP21 silencing in LNCaP prostate cancer cells decreased PCA3 and androgen receptor (AR) transcriptional levels and increased prune homolog 2 (PRUNE2) coding gene expression, indicating effective involvement of ARHGAP21 in androgen-dependent tumor pathway." (PMID 38896642, 2024).
breast carcinoma (2 papers, 2014 to 2021). "Evidence showed that as a PDZ domain containing protein, ARHGAP21 could interact with the PDZ-binding motif of Claudin-2, in such way promoted breast cancer liver metastasis." (PMID 34211100, 2021).
deafness (2 papers, 2023). An inherited or acquired condition characterized by the complete loss of the ability to hear from one or both ears. "There were 18 genes linked only to Metabolic hearing loss (including four deafness genes: DMD, DUOX2, CELSR1 and ELMO3) and 54 genes linked only to Sensory hearing loss (including four deafness genes: ARHGAP21, LMO7, UBE3B and ADGRV1)." (PMID 38011198, 2023). "PKHD1L1, DUOX2, CELSR1, ELMO3, ARHGAP21, LMO7 and UBE3B are all defined as deafness genes through work on the mouse orthologues." (PMID 37163093, 2023).
Obesity (2 papers, 2019 to 2020). Accumulation of substantial excess body fat. "Thus, ARHGAP21 protein emerges as an important candidate to be considered for the prevention and treatment of obesity and associated diseases." (PMID 31191459, 2019). "However, further studies are necessary to better understand by which mechanism ARHGAP21 acts in metabolic diseases, such as obesity and diabetes." (PMID 33324349, 2020). "This suggests a new role for ARHGAP21 in energetic metabolism and prompts us to consider GAP protein members as possible targets for the prevention and treatment of obesity and related diseases." (PMID 31191459, 2019).
cholangiocarcinoma (1 paper, 2023). A carcinoma that arises from the intrahepatic biliary tree (intrahepatic cholangiocarcinoma) or from the junction, or adjacent to the junction, of the right and left hepatic ducts (hilar cholangiocarcinoma). "In the study, our research found the biological effect of ARHGAP21 on cholangiocarcinoma and identified that it could significantly influence the proliferation and migration ability of CCA cells." (PMID 36676763, 2023). "Rho GTPase-activating protein 21 (ARHGAP21) is one of the RhoGAPs and its role in cholangiocarcinoma (CCA) has never been disclosed in any publications." (PMID 36676763, 2023).
colon cancer (1 paper, 2023). "Low expression of ARHGAP21 has been shown to correspond with worse prognosis in prostate, lung, ovarian, and colon cancer." (PMID 37895233, 2023).
diabetes mellitus (1 paper, 2020). A metabolic disorder characterized by abnormally high blood sugar levels due to diminished production of insulin or insulin resistance/desensitization. "Therefore, based on these finds, ARHGAP21 may be an important target in Diabetes Mellitus (DM) treatment." (PMID 33324349, 2020).
dilated cardiomyopathy (1 paper, 2015). Cardiomyopathy which is characterized by dilation and contractile dysfunction of the left and right ventricles. "Interestingly a gene paralog, ARHGAP21, was also identified as a candidate gene of interest in Irish Wolfhounds with dilated cardiomyopathy." (PMID 26509595, 2015).
hepatocellular carcinoma (1 paper, 2026). A malignant tumor that arises from hepatocytes. "Rho GTPase-activating protein 21 (ARHGAP21) plays a role in the occurrence and development of certain cancers, but its function in hepatocellular carcinoma (HCC) remains unclear." (PMID 41957357, 2026).
Insulin resistance (1 paper, 2024). Increased resistance towards insulin, that is, diminished effectiveness of insulin in reducing blood glucose levels. "Top DEGs, including SERPINE1 and ARHGAP21, have also been linked to metabolic syndrome or its features (e.g. insulin resistance) in humans and animal models." (PMID 39531449, 2024).
intrahepatic cholangiocarcinoma (1 paper, 2023). A carcinoma that arises from the intrahepatic bile duct epithelium in any site of the intrahepatic biliary tree. "Our study found that ARHGAP21 was highly mutated in intrahepatic cholangiocarcinoma from the cBioPortal website and it was negatively correlated with pDC by estimating with the ssGSEA algorithm." (PMID 36676763, 2023).
Myelodysplasia (1 paper, 2021). Clonal hematopoietic stem cell disorders characterized by dysplasia (ineffective production) in one or more hematopoietic cell lineages, leading to anemia and cytopenia. "Interesting, we found increased ARHGAP21 gene expression in MSCs derived from BM cells of de novo AML patients in comparison with HD and patients with MDS or AML developed after myelodysplasia." (PMID 34917608, 2021).
prostate adenocarcinoma (1 paper, 2023). "For example, ARHGAP21 was considered a RhoGAP for RhoA, and RhoC contributed to the proliferation and migration of prostate adenocarcinoma cells." (PMID 36676763, 2023). "Similar results were also reported in the previous study that ARHGAP21 is overexpressed in prostate adenocarcinoma cells and in head and neck squamous carcinomas." (PMID 36676763, 2023).
tumor (9 papers, 2017 to 2026). "Overexpression of FLNA reversed the cytoskeleton remodeling-related suppression of tumor metastasis in ARHGAP21-knockdown HCC cells." (PMID 41957357, 2026). "A significant association was detected between ARHGAP21, ARHGAP26, ARHGAP27, ARHGAP 34, ARHGAP 35, ARHGAP42, and ARHGAP46 and the tumor stages." (PMID 38783033, 2024). "Three GEO datasets were applied to validate the over-expression of ARHGAP21 in tumor tissue (GSE26566: p = 3.7 × 10−11; GSE45001: p = 0.04; GSE107943: p = 2.6 × 10−12)." (PMID 36676763, 2023). "Since its discovery, ARHGAP21 was explored constantly and found it was involved in tumor progression by regulating Rho-GTPase activities." (PMID 36676763, 2023). "In this study, we emphasized the carcinogenesis of ARHGAP21 in CCA tumor development." (PMID 36676763, 2023). "In summary, ARHGAP21 has a potential effect on different tumorigenesis and tumor progression." (PMID 36676763, 2023). "Moreover, MEC-17-induced attenuation of cell migration was rescued after application of CASIN by the wound healing and Transwell assay, suggesting that MEC-17 determined cell morphology, migration and invasion ability, and tumour metastasis through ARHGAP21-mediated cdc42 activation." (PMID 30504808, 2018). "ARHGAP21 and IGHG1 were strongly expressed in both stromal and tumor cells, and therefore excluded from further study." (PMID 31533654, 2019). "Stably expressing MEC-17 cells, which showed asthenic tumour metastatic ability, exhibited suppression of EMT, redistribution of cell polarization, higher cdc42 activity, and downregulation of Rho-GAP, ARHGAP21." (PMID 30504808, 2018). "In summary, the study identified that ARHGAP21 promotes the proliferation and migration of CCA cells via the PI3K/Akt pathway, and it may be the key immune-related regulator in the tumor microenvironment of CCA." (PMID 36676763, 2023). "Three URs (ARHGAP21, KLF4, TBK1), among those that discriminated responding and non responding patients in the baseline tumor samples, lost significance in subsequent biopsies, possible reflecting the shift in the transcriptomic programs of the neoplastic lesions occurring as result of therapy." (PMID 36397155, 2022). "In addition, overexpression of MEC-17 inhibited tumour metastasis, suppressed EMT, and disturbed cell polarization through cdc42 activation resulting from decreased expression of Rho-GAP, ARHGAP21." (PMID 30504808, 2018). "Therefore, we supposed that ARHGAP21 may be an essential regulator for angiogenesis and immune infiltration in the CCA tumor microenvironment." (PMID 36676763, 2023).
cancer (7 papers, 2014 to 2026). A tumor composed of atypical neoplastic, often pleomorphic cells that invade other tissues. "The results of Genomics of Drug Sensitivity in Cancer (GDSC) further validate the relationship between ARHGAP21 and the PI3K/Akt signaling pathway." (PMID 36676763, 2023). "It indicated that ARHGAP21 not only contributed to embryonic progression but also directly or indirectly affected cancer progression through some pathways." (PMID 36676763, 2023). "ARHGAP21, a negative regulator of cancer cell growth, migration, and invasion, and ADAMTSL3, essential for the development and growth of lymphatic vessels, have been reported to have increased methylation levels in high-Gleason-score PCa in African Americans." (PMID 37895233, 2023). "The online database analysis verified that ARHGAP21 was upregulated in most human cancers and especially in CCA it is highly expressed." (PMID 36676763, 2023). "Studies have reported that ARHGAP21 is a negative regulator of cancer cell growth, migration, and invasion." (PMID 37895233, 2023). "It was identified that ARHGAP21 was differentially expressed and played different roles in multiple human cancers." (PMID 36676763, 2023). "The expression of ARHGAP21 in various cancers was analyzed and showed that the ARHGAP21 mRNA of tumors was upregulated (p < 0.0001)." (PMID 36676763, 2023). "This suggests that ARHGAP21 may play different roles in different cancers, and it seems to have an important effect on the carcinogenic mechanism of CCA." (PMID 36676763, 2023). "Moreover, the function of ARHGAP21 is not only reflected in the effect on cancer but also acts significantly in the regulation of glucose homeostasis, intracellular Golgi transport, and viral replication." (PMID 36676763, 2023). "Studies have shown that ARHGAP21 may be involved in cell differentiation, a procedure that can give rise to cancer when disrupted." (PMID 36676763, 2023). "Furthermore, morphological change and migration inhibition of cancer cells were accompanied by EMT repression, Golgi reorientation, and polarity disruption caused by alteration of cdc42 activity via a decrease in Rho-GAP, ARHGAP21." (PMID 30504808, 2018). "Although many studies have described a variety of important biological functions of ARHGAP21 in cancers, its role in CCA has not been reported." (PMID 36676763, 2023). "However, there are few studies about the biological effects of ARHGAP21 on cancer so far, and no article has reported the biological effects of ARHGAP21 on CCA." (PMID 36676763, 2023).
ARHGAP21 also shares sentences with these, for which no sentence is quoted: colorectal cancer (2 papers); Sensory hearing loss (2); glioblastoma (1); lung squamous cell carcinoma (1); metabolic syndrome (1); ovarian tumors (1); pituitary tumor (1).